PPARG (peroxisome proliferator activated receptor gamma)
Diseases named in the same sentence as PPARG in open-access papers (continued):
Sharing a sentence is not in itself a finding about the gene and the disease.
Obesity (continued). "Accordingly, modulation of PPARγ and PPARα is very important for tackling lipid metabolic disorder associated with obesity." (PMID 28248545, 2017). "Abnormalities in PPARγ expression has been found to be associated with the loss of insulin sensitivity in obesity and Type2 diabetes indicating insulin regulation of PPARΥ expression." (PMID 28072841, 2017). "Mounting evidence suggests that peroxisome proliferator-activated receptor gamma (PPAR-γ) controls the inflammatory potential of monocytes/macrophages, with net impact on the course of obesity-associated inflammation." (PMID 28993702, 2017). "Two of the mutations in the PPARG gene have been shown to be associated with obesity or diabetes-related phenotypes in different populations." (PMID 28953253, 2017). "This study investigated the impact of additional PPARG gene-obesity interaction on T2DM risk based on a Chinese population by using GMDR model." (PMID 28123453, 2017). "So the aim of this study was to investigate the association of PPARG, and additional PPARG gene- obesity interaction with T2DM risk based on a Chinese population." (PMID 28123453, 2017). "Peroxisome proliferator-activated receptor γ (PPARγ) is the master regulator of adipocyte differentiation and is closely linked to the development of obesity." (PMID 29233982, 2017). "In fact, GW9662 has an anti‐obesity effect in mice, while mice heterozygous for PPARG deficiency show improved insulin sensitivity." (PMID 28275008, 2017). "PPARγ also regulates adipogenesis, and its polymorphisms have been suggested to be a risk for obesity." (PMID 28678155, 2017). "A previous study by Odegaard and colleagues showed that PPARγ deficiency in macrophages impairs M2 macrophage activation and predisposes the animals to development of diet-induced obesity, insulin resistance, and glucose intolerance." (PMID 27379017, 2016). "Our studies highlight the association (in terms of timing and tissue-specificity) of obesity-related clock gene disruption with altered PPARα and PPARγ expression and local tissue inflammation." (PMID 27439882, 2016). "Both PPARγ and PPARδ expressions are negatively associated with obesity, where they modulate adipogenesis and lipid oxidation, respectively." (PMID 27379017, 2016). "In children diagnosed with T2D the Pro12Ala polymorphism of PPARγ was significantly associated with obesity and T2D." (PMID 27483259, 2016). "The authors of the study suggested that this phenomenon is related to the obesity-associated unphosporylation of PPARγ that induces a set of target genes which can promote insulin sensitivity." (PMID 27104517, 2016). "Macrophage-directed PPARγ KO mice are more predisposed to obesity and insulin resistance after challenged with HFD, however these mice do not have liver steatosis." (PMID 27483259, 2016). "The polymorphism PPARG Pro12Ala (rs1801282) has been studied indifferent populations with contradictory results; in some studies Ala allele wasassociated with obesity, whereas in a Chinese population, it was reported as a protecting factor." (PMID 27560839, 2016). "Disruption of PPARγ predisposes mice to the development of diet-induced obesity, insulin resistance, and glucose intolerance, whereas activation of PPARγ within macrophages promotes lipid efflux." (PMID 26901760, 2016). "This association is supported by almost all sources, and by >100 articles, which mostly explore the role of PPARG genetic variants in Obesity." (PMID 25877637, 2015). "PPARG is one of the most replicated diabetes and obesity genes, with sequence variants strongly associated with obesity and T2D." (PMID 25806089, 2015). "Macrophage-specific disruption of PPARγ impairs development of alternatively activated M2 phenotype and predisposes individuals to diet-induced obesity." (PMID 26339623, 2015).
Obesity (continued). "Genetic mutations or polymorphisms and altered signaling or expression of PPARG has been associated with decreased insulin action, obesity, dyslipidemia, as well as cardiovascular disease and cancer." (PMID 26606528, 2015). "DisGeNET associates PPARG to >300 diseases, although only two of them, Obesity and Lipodystrophy, Familial Partial, Type 3 (FPLD3), stem from two expert-curated resources, UniProt and CTD." (PMID 25877637, 2015). "For instance, variants in and around PPARG have been associated with T2D, monogenic obesity and WHRadjBMI." (PMID 26363598, 2015). "Following these reports, we also observed that administration of a PPARγ antagonist to HFD-fed mice diminished HFD-induced obesity and fatty liver disease while being associated with the restoration of eNOS expression in adipocytes." (PMID 26317347, 2015). "PPARγ is associated with obesity while decreased HNF4α is associated with fatty liver in mice and diabetes in humans." (PMID 26200659, 2015). "In previous studies, there was correlation between obesity (BMI) and VO2max (r = −0.88, P < 0.05) in young subjects and a strong positive correlation between the ratio of PPARG (splice variants y2/y1) mRNA and the BMI (r = 0.70, P < 0.001) in obese patients." (PMID 25879043, 2015). "PPARγ is implicated in various metabolic disorders, including obesity, insulin resistance, and dyslipidemia." (PMID 25709707, 2015). "An association of PPARG gene variants with insulin resistance, type 2 diabetes, obesity, and hypertension has been shown." (PMID 25879043, 2015). "The aim of the present study was todetermine the possible association of five single-nucleotide polymorphisms (SNPs)located in the IGF2, LEPR, POMC,PPARG, and PPARGC1genes with obesity orobesity-related risk phenotypes." (PMID 25923461, 2015). "The loss of PPARγ in immune cells impaired their ability to modulate glucose homeostasis and obesity-related inflammation." (PMID 26714018, 2015). "It has been well established that upregulated expression and activity of PPARγ can exert a positive effect on dysregulated adipose tissue function associated with obesity." (PMID 24817881, 2014). "Our results suggested a possible mechanism underlying the role of Twist 1 in obesity that is based on the multiple biological functions of PPARγ." (PMID 25128964, 2014). "Variants at the CTNNBL1, LEPR and PPARG loci demonstrated nominal association with obesity phenotypes (meta-analysis P-values ranging from 1.15×10−3 to 4.94×10−2)." (PMID 24879436, 2014). "The two common variants of the PPARG gene, Pro12Ala and His447His, have been associated with metabolic states of obesity, insulin resistance, type 2 diabetes, and metabolic syndrome." (PMID 25197274, 2014). "For example, macrophage-specific PPARγ deficiency impaired M2 macrophage polarization and predisposed the mice to HF diet-induced obesity." (PMID 24911652, 2014). "All of the results received during genetic associations studies should be interpreted with caution, especially considering diverse data obtained for the correlations of obesity predisposition and PPARG Pro12Ala polymorphism in different human populations." (PMID 25371663, 2014). "A number of polymorphisms have been described in the association of the PPARα and PPARγ isoforms with obesity." (PMID 23545576, 2013). "The fact that p-F11 exhibits partial efficacy in activating PPARγ, but increases adiponectin secretion and inhibits obesity-linked phosphorylation of PPARγ, makes it a potential therapeutic agent for the treatment of type 2 diabetes." (PMID 24454336, 2013). "Macrophage specific PPARγ deletion led to diet associated obesity, insulin resistance, and glucose intolerance." (PMID 23554810, 2013). "Because PPARγ regulates adipocyte differentiation and controls body fat storage, the relevance of the PPARγ polymorphism in the context of susceptibility to obesity is of major interest." (PMID 23799144, 2013).
Obesity (continued). "The peroxisome proliferator-activated receptor-γ (PPARγ) is implicated in numerous diseases including Alzheimer’s disease, obesity, diabetes, atherosclerosis and cancer." (PMID 24147038, 2013). "Dysregulation of PPAR-gamma (PPARγ) is linked to the development of obesity, type 2 diabetes, atherosclerosis and other disease conditions." (PMID 23389305, 2013). "We illustrate that PPARγ ability to alleviate obesity-associated inflammation raises an interesting pharmacologic potential." (PMID 23577023, 2013). "Amongst NRs, PPAR-gamma (PPARG) has been implicated in the pathology of numerous diseases including obesity, diabetes, atherosclerosis, and cancer." (PMID 24391967, 2013). "Computational analyses by us and generation of gene-disease network suggests that PPARγ is implicated in pathology of several diseases including cancer, diabetes, and obesity." (PMID 23431283, 2013). "PPARγ is strongly associated with obesity because it is highly expressed in white fat depots and it serves as a target for certain anti-diabetic drugs." (PMID 23577023, 2013). "This is in-line with small candidate gene-by-environment interaction studies e.g. of saturated fat intake with PPARG variants for obesity-related traits, including differential effects by sex." (PMID 23754948, 2013). "Activation of hypothalamic PPARα and/or PPARγ has been implicated in weight gain and obesity, potentially consistent with elevated adiposity and DIO in PPARδ KO mice." (PMID 22916190, 2012). "Bone and fat cells share a common origin and activation of PPARγ with diet-induced obesity is associated with decreased bone density, increased expression of PPARγ in bone, increased bone marrow adipogenesis and decreased expression of Runx2." (PMID 22260224, 2012). "PPARG has been implicated in the pathology of numerous diseases including obesity, diabetes, atherosclerosis, and cancer." (PMID 22969728, 2012). "In this study, we establish a link between free fatty acids (FFAs) and PPARγ in the context of obesity-associated inflammation." (PMID 22529965, 2012). "While, in non HIV-infected patients, the effects of PPARγ C1431T polymorphism on metabolic syndrome varied in different studies, the majority of them indicated the association of C1431T polymorphism with obesity and hyperglycemia." (PMID 23145084, 2012). "PPARγ has been implicated in the pathology of numerous diseases including obesity, diabetes, atherosclerosis and cancer." (PMID 22848576, 2012). "Activation of this receptor with HF feeding or a chemical agonist increases weight gain, raising the possibility, at least, that HFD consumption activates neuronal PPARγ as a pathogenic mechanism in obesity." (PMID 22916190, 2012). "PPARγ appears to be a key regulator of energy balance, with polymorphisms on the PPARγ gene linked to obesity and effects on body composition." (PMID 22168210, 2011). "In humans, an activating mutation in PPARγ leads to increased adipogenesis and obesity, while inactivating mutation results in a lower body mass." (PMID 20182546, 2010). "Genetic studies are also consistent with a role of PPARγ Ser-112 in fat metabolism and glucose homeostasis, as S112A knock-in mice exhibit increased PPARγ activity with protective effects from obesity-associated insulin resistance." (PMID 19888469, 2009). "Single nucleotide polymorphisms (SNPs) in the peroxisome proliferator-activated receptor γ (PPARG) gene have been associated with cardiovascular risk factors, particularly obesity and diabetes." (PMID 20016803, 2009). "The general role for PPARγ in the regulation of lipidmetabolism is underlined by the therapeutic utilization of the PPARγ ligandsthiazolidinediones in obesity-linked type II diabetes." (PMID 18551184, 2008). "Paradoxically, studies reveal that a moderate reduction of PPARγ activity as observed in heterozygous PPARγ-deficient mice, or the Pro12Ala polymorphism in human PPARγ gene, prevent insulin resistance and obesity induced by a high-fat diet." (PMID 18302760, 2008).
Obesity (continued). "Examinations of naturally occurring human polymorphisms have focussed on susceptibility toType II diabetes, insulin sensitivity, and obesity, and to date at least sevenpolymorphisms within the PPARG gene have been described." (PMID 18309368, 2008). "PPARγ is mainly expressed in white adipose tissue (WAT). the deficiency of PPARγ inadipose tissue is protective against obesity and insulinresistance caused by HFD." (PMID 17389764, 2007). "Several mutations have been discovered in PPARG in humanand have been investigated for their role in obesity, diabetes,and metabolic syndrome and as such are reviewed elsewhere." (PMID 17347532, 2006). "By comparing lipidomic profiles and PPARγ expression across these depots, our investigation provides a comprehensive understanding of how plasma FAs differentially modulate adipose tissue biology and contribute to obesity‐related metabolic risk." (PMID 40968591, 2025). "Fat mass and obesity-associate genes (FTO) affect obesity risk and energy regulation, peroxisome proliferator-activated receptor gamma (PPARG) impacts glucose regulation and cellular differentiation, and insulin receptor substrate 1 (IRS1) modulates insulin signaling pathways." (PMID 40076293, 2025). "Moreover, CYP1B1 deficiency attenuated HFD‐induced obesity and improved glucose tolerance due to the reduced expression of different adipogenic genes such as PPARγ, CD36, FAS, and SCD‐1 and increased expression of genes involved in lipolysis." (PMID 39806854, 2025). "The PPARγ signaling pathway is a key mediator in the association between obesity and pollution." (PMID 39825581, 2025). "Furthermore, freeze-dried kimchi cabbage and onion regulated lipid metabolism by inhibiting lipid accumulation and modulating obesity-associated mRNA/protein expression related to the C/EBPα and PPARγ pathways." (PMID 41189663, 2025). "Dysfunction in PPARγ is closely linked with insulin resistance and obesity." (PMID 40968591, 2025). "Changes in plasma FA profiles are linked to PPARγ gene expression, especially in obesity, indicating dietary FAs may affect metabolic regulation and health." (PMID 40968591, 2025). "Obesity may result from increased fat accumulation caused by PPARγ activation, particularly when it is dysregulated." (PMID 40066031, 2025). "Interestingly, recent preclinical studies indicate that obesity causes a reduction in PPARγ expression in white adipose tissue." (PMID 40149950, 2025). "Consequently, SIRT1 and PPARγ have emerged as promising therapeutic targets for managing male infertility associated with obesity and metabolic syndrome." (PMID 41445731, 2025). "While most GFP-labeled adipocyte nuclei robustly expressed PPARγ proteins under typical conditions, a significant proportion of adipocyte nuclei from eWAT in HFD-fed mice lacked PPARγ proteins, confirming the presence of PPARγ-deficient Ad6 adipocytes in eWAT during obesity." (PMID 38645263, 2024). "Furthermore, OSA is characterized by metabolic dysfunction and obesity, and the PPARG gene is implicated in the regulation of lipid metabolism and glucose homeostasis." (PMID 38443855, 2024). "PPARG encodes protein, PPAR‐gamma, a member of the peroxisome proliferator‐activated receptor subfamily of nuclear receptors, and participates in the pathology of numerous diseases like obesity, diabetes, atherosclerosis, and cancer." (PMID 39107932, 2024). "Consequently, decreased or silenced PPARγ expression results in impaired adipocyte differentiation and lipid metabolism, potentially contributing to an elevated risk of obesity due to increased fat accumulation." (PMID 39421300, 2024). "PPARγ is a TF that has been implicated in the pathology of obesity, diabetes, and NAFLD." (PMID 39338294, 2024). "This may affect thermogenesis by downregulating the expression of Pparγ, Prdm16, and Pgc1α, thereby reducing energy and heat production, which in turn contribute to obesity and diminished metabolism associated with menopause." (PMID 38397839, 2024).
Obesity (continued). "In addition, the G allele of PCSK1 SNP rs6235 was individually associated with obesity and metabolic syndrome, and the G allele of PPARG rs1801282 was associated with obesity." (PMID 37761915, 2023). "Additionally, obesity causes disruption of the adipocyte clock via inhibition of PPARγ, which regulates adipogenesis and leads to the downregulation of Bmal1 and other clock genes." (PMID 37626963, 2023). "Moreover, for the first time the rs12495364-TC in the PPARG gene was associated with glycemic, lipid, obesity, and periodontal parameters." (PMID 37047733, 2023). "Furthermore, previous studies have demonstrated a significant association between high PPARG expression and poor prognosis in pancreatic ductal adenocarcinoma, with two key contributing factors being obesity and diabetes." (PMID 38044948, 2023). "Notably, recent investigations have revealed an unfavorable prognostic association between overexpression of PPARG and certain cancer types (e.g., prostate cancer, esophageal cancer), particularly those linked to obesity." (PMID 38154113, 2023). "Therefore, the reduction in PPARγ is associated with the suppression of adipogenesis, which is considered an anti-obesity effect." (PMID 38139853, 2023). "In white adipose tissue, hypomethylation contributes to increased Pparγ expression, causing lipid accumulation and adipocytogenesis; whereas in brown adipose tissue, it decreases Pparγ expression, impairing its maturation, which leads to loss of ability to resist obesity and aggravates systemic IR." (PMID 37484964, 2023). "All these findings show that GN can cause obesity by interacting with PPARγ." (PMID 38098865, 2023). "ANKO mice display an increased VAT PPARg (peroxisome proliferator-activated receptor gamma) Ser273 phosphorylation, a post-translation modification that impairs its insulin-sensitizing effects and modulated expression of most of its obesity-linked targets at the mRNA level." (PMID 37761000, 2023). "For example, in line with how PPARγ has been implicated in the pathophysiology of obesity and type 2 diabetes, mutations in the gene encoding PPARγ may impact the severity or susceptibility of OKD and CKD in general." (PMID 37760939, 2023). "PPARγ is closely associated with obesity, adipocyte differentiation and IR." (PMID 35407014, 2022). "In conclusion, the present study demonstrated that obesity-induced downregulation of PPARγ may increase susceptibility to ALI." (PMID 36213491, 2022). "Similarly, SalB, another potent active water-soluble component in Salvia miltiorrhiza, impedes PPARγ expression and adipogenesis, thus attenuating weight gain and obesity-associated metabolic disorders." (PMID 36127704, 2022). "Generally, the existing data demonstrate that both life-long and prenatal PCB exposure may be considered as a risk factor for obesity due to the increased expression of adipogenic regulators PPARγ and C/EPBα, as well as C/EPBβ." (PMID 35202251, 2022). "PPARγ was strongly associated with overweight and obesity in women." (PMID 36551995, 2022). "In addition, the decrease in SIRT1 forces increased expression of peroxisome proliferator-activated receptor gamma (PPARγ), which, through the stimulation of expression for a number of genes, causes an accumulation of lipids in adipocytes and obesity." (PMID 36117520, 2022). "Therefore, it is natural that the differentiation of the PPARG gene, and in particular, the functional significance of the Pro12Ala variants in relation to body weight measured by BMI and susceptibility to obesity have been the subject of numerous studies." (PMID 36558537, 2022). "Meta-analysis between the rs1801282 polymorphism in PPARG and obesity indexes." (PMID 35846293, 2022). "However, the impact of PPARG SNPs on the obesity risk in children has been scarcely studied, literature data reporting mostly associations with adulthood obesity and its related complications." (PMID 36466447, 2022).